STK24 (serine/threonine kinase 24)
Diseases named in the same sentence as STK24 in open-access papers (continued):
Sharing a sentence is not in itself a finding about the gene and the disease.
pancreatic cancer (1 paper, 2024). "The attenuation of STK24 expression emerges as a suppressive factor in the growth of tumors including colorectal, lung, and pancreatic cancer cells, particularly in immunocompetent mice." (PMID 38229183, 2024). "Moreover, immunofluorescence staining for CD8 and GZMB revealed a significant augmentation of GZMB+CD8+ T cells in CRC or pancreatic cancer patients with low expression of STK24." (PMID 38229183, 2024).
Polyuria (1 paper, 2021). An increased rate of urine production. "Here, we found that mice deficient of Pdcd10 or Stk24/25 in the kidney tubules developed polyuria and displayed increased water consumption." (PMID 34156031, 2021).
rectum adenocarcinoma (1 paper, 2024). An adenocarcinoma arising from the rectum. "A similarly enhanced STK24 gene expression pattern is also seen in PAAD and rectum adenocarcinoma (READ) from the GEPIA data set." (PMID 38229183, 2024).
schizophrenia (1 paper, 2023). A major psychotic disorder characterized by abnormalities in the perception or expression of reality. "STK24 has been implicated in unipolar depression and schizophrenia." (PMID 36959830, 2023).
temporal lobe epilepsy (1 paper, 2020). A localization-related (focal) form of epilepsy characterized by recurrent seizures that arise from foci within the temporal lobe, most commonly from its mesial aspect. "In the present study, we used samples from patients with temporal lobe epilepsy, pentylenetetrazole‐kindled mice, and Mg2+‐free‐induced epileptic cultured hippocampal neurons to detect the expression pattern of STK24." (PMID 32436359, 2020).
cancer (17 papers, 2016 to 2025). A tumor composed of atypical neoplastic, often pleomorphic cells that invade other tissues. "Results of Western blot and enzyme-linked immunosorbent assay (ELISA) analysis revealed that overexpression of STK24 promotes secretion of VEGFA by cancer cells, whereas the loss of STK24 decreased the secretion of VEGFA by the cells." (PMID 36720310, 2023). "In previous studies, the roles of STK24/MST3 have been implicated in the control of cancer cell migration and the regulation of neutrophil degranulation 8-10." (PMID 31892988, 2020). "Similarly, tumors induced by cancer cells stably expressing STK24+shnc were much bigger than tumors induced by cancer cells stably expressing vector+shnc, with the loss of STAT3 reversing STK24-mediated tumor progression." (PMID 36720310, 2023). "The findings hence provide a novel insights into the mechanism of STK24 action and reveal the underlying mechanism of tumor angiogenesis, as well as provide the expected guidance to the future development of therapeutic strategies for cancer treatment." (PMID 36720310, 2023). "Moreover, it was revealed that loss of STK24 inhibited expression of cyclin D and vimentin and promoted expression of E-cadherin in the cancer cells." (PMID 36720310, 2023). "Our investigation illuminates the multifaceted role of STK24 in tumorigenesis, extending beyond cancer cell autonomy." (PMID 38229183, 2024). "Together, these results strongly suggest that STK24 is broadly upregulated across many cancer types and is indicative of poor prognosis." (PMID 38229183, 2024). "Collectively, these findings strongly indicate that STK24 expression levels exhibit a consistent elevation across diverse cancer types, thereby correlating with poor outcomes." (PMID 38229183, 2024). "The STK24 expression levels were also higher in tissues of other cancers types as compared with the matched normal tissues." (PMID 36720310, 2023). "The CMs that were obtained from cancer cells stably expressing vector+shnc, STK24+shnc, STK24+shSTAT3#1, or STK24+shSTAT3#2 were used to maintain HUVECs." (PMID 36720310, 2023). "Cancer cells stably expressing vector+shnc, STK24+shnc, STK24+shSTAT3#1, or STK24+shSTAT3#2 were subcutaneously injected into 4-week-old male nude BALB/c mice." (PMID 36720310, 2023). "Recent studies have shown that serine/threonine-protein kinase 24 (STK24) plays an important role in cancer development." (PMID 37181807, 2023). "It was found that STK24 overexpression promotes invasion and migration of cancer cells, which was consistent with the results obtained in the wound healing assays." (PMID 36720310, 2023). "The current study also investigated if STK24 regulates the secretion of VEGFA by cancer cells because VEGFA is an essential factor of tumor angiogenesis." (PMID 36720310, 2023). "The successful suppression of the STK24 protein in M12 cancer cells was demonstrated by western blotting." (PMID 31892988, 2020). "The quantitative evaluation of the STK24 protein was performed in whole tissues, including cancer cells, stromal tumor-infiltrating cells, and blood cells." (PMID 31892988, 2020). "Here, STK24 is identified as a promoter of tumorigenesis in a non‐cancer cell‐autonomous manner." (PMID 38229183, 2024). "In conclusion, findings of the current study showed that STK24 acts as an oncogene, and the expression of STK24 in cancer cells is positively correlated with the proliferation, migration, invasion, and tumor angiogenesis potential of cancer cells." (PMID 36720310, 2023). "Thus, the bioinformatic analyses using the Kaplan‐Meier Plotter and Oncomine databases indicate that STK24 expression was involved in cancer progression." (PMID 31892988, 2020). "Given the importance of a functional immune system for the effects of STK24 on tumor formation, we further investigated whether cancer cell-secreted cytokines were involved in the tumor microenvironment." (PMID 31892988, 2020).
cancer (continued). "We hypothesized that STK24 inhibits the secretion of pro-inflammatory cytokines by cancer cells." (PMID 31892988, 2020). "Consistently, it was noted that the gain of STK24 increased expression levels of STAT3 in A549 and H226 cancer cells." (PMID 36720310, 2023). "For solid tumors, STK24 positively regulates ERK1/2 activation and cooperates with STK26 and YSK1 to promote migration and metastasis of the cancer cells." (PMID 36720310, 2023). "To understand whether this finding is also conserved across other cancer types, we used the entire Cancer Cell Line Encyclopedia mRNA expression dataset to obtain the co-expression of all the pairwise combinations of C4orf19, PDCD10, STK24, STK25, and STK26." (PMID 38517886, 2024). "Further attesting to our conclusions, we observed an upregulation of STK24 expression in various tumor tissues, correlating with poor survival of patients as well as the intratumoral infiltration of activated CD8+ T cells in human cancer tissues." (PMID 38229183, 2024). "In present study, the suppression of STK24 did not affect the cell proliferation of M12 cancer cell in vitro." (PMID 31892988, 2020). "Therefore, the suppression of STK24 did not affect the cell growth rates of the mouse M12 cancer cell lines." (PMID 31892988, 2020).
tumor (15 papers, 2016 to 2025). "Consistently, the levels of STK24 are inversely associated with the number of cytotoxic CD8+ T cells in human tumor tissues." (PMID 38229183, 2024). "Meanwhile, Stk24 deficiency in CT26 or MC38 tumor cells combined with the anti‐PD1 therapy strongly boosted the intratumoral infiltration and activation of CD8+T or NK cells." (PMID 38229183, 2024). "To determine the mechanisms underpinning the anti‐tumor immune response mediated by STK24, we examined immune cell profiles in both control and Stk24‐deficient CT26 or KPC tumors." (PMID 38229183, 2024). "Experimental evidence gathered from murine tumor models and patient specimen indicates that STK24 deficiency in tumor cells suppresses tumor growth by orchestrating infiltration of activated CD8+ T cells and NK cells." (PMID 38229183, 2024). "Here, the deficiency of serine‐threonine kinase STK24 is observed in tumor cells causing substantial attenuation of tumor growth in murine syngeneic models, a process relying on cytotoxic CD8+ T and NK cells." (PMID 38229183, 2024). "We found that STK24 deficiency in tumor cells significantly impaired the phosphorylation of AKT, but not STAT1 and STAT3 when cells were exposed to IFN‐γ." (PMID 38229183, 2024). "Mechanistically, STK24 in tumor cells associates with and directly phosphorylates AKT at Thr21, which promotes AKT activation and subsequent PD‐L1 induction." (PMID 38229183, 2024). "The STK24 knockdown cells were implanted into NOD/SCID mice separately, and the results showed that STK24 knockdown significantly promoted tumor growth to some extent in T- and B-cell immunity-deficient mice." (PMID 31892988, 2020). "Recent studies have found that the expression of the serine–threonine kinase (STK24), which regulates tumor immune escape by promoting AKT phosphorylation and PD‐L1 expression, is upregulated in tumor specimens." (PMID 39778021, 2025). "Quantification of the IHC results indicated a substantial increase in STK24 protein expression within tumor tissues compared to corresponding tumor margins in CRC, LUAD, and PAAD patients." (PMID 38229183, 2024). "In MC38 cell‐inoculated mice, Stk24 deficiency boosted the proportion of active IFN‐γ+ CD8+ T cells and IFN‐γ+ NK cells in the tumor tissues." (PMID 38229183, 2024). "Subsequently, we tested tumor formation of the Stk24 mutants in syngeneic immuno‐competent mice by inoculating mouse Ctrl or Stk24 KO CT26 cells into BALB/c mice." (PMID 38229183, 2024). "In human NCI‐H1299, A549, and HCT116 tumor cells, STK24 knockdown or knockout also inhibited IFN‐γ‐induced PD‐L1 expression." (PMID 38229183, 2024). "Collectively, these findings strongly indicate that STK24 mediates tumor immune escape in a tumor PD‐L1 expression‐dependent manner." (PMID 38229183, 2024). "To validate the observations from the patient cohorts, we analyzed STK24 expression status using Tumor Immune Estimation Resource (TIMER) databases, The Human Protein Atlas (HPA), and Gene Expression Profiling Interactive Analysis (GEPIA) databases." (PMID 38229183, 2024). "To examine the functional role of Stk24 in tumor cells, we generated Stk24 knockout mutants by CRISPR‐Cas9 targeting or Stk24 knockdown cell lines by siRNA or small hairpin RNAs (shRNAs) in diverse mouse cell lines." (PMID 38229183, 2024). "To determine the potential of STK24 inhibition as a strategy for overcoming tumor immune evasion in vivo, we investigated the delivery of exogenous Stk24 siRNA into tumor tissues to enhance the immunotherapeutic effect." (PMID 38229183, 2024). "In conclusion, our study revealed the pivotal role of STK24 in orchestrating tumor immune evasion responses by phosphorylating AKT and promoting PD‐L1 expression." (PMID 38229183, 2024). "Tumor tissues were then divided into groups with high or low levels of STK24 according to IHC scores, patients with high STK24 protein expression exhibited shorter overall survival." (PMID 38229183, 2024).
tumor (continued). "We further identified that STK24 augments PD‐L1 expression in tumor cells via phosphorylating AKT at a previously unrecognized Thr21 residue." (PMID 38229183, 2024). "Collectively, these results further indicate that STK24 inhibits anti‐tumor immune response via regulating PD‐L1 expression and AKT Thr21 phosphorylation." (PMID 38229183, 2024). "Given that STK24 facilitates tumor immune evasion through its kinase activity, the prospect of employing small molecules specifically designed to target STK24 enzyme activity is a plausible strategy for combination therapy with an immune‐checkpoint blockade." (PMID 38229183, 2024). "Inhibition of STK24 expression decreased the ability of KLF5 to promote tumor proliferation and metastasis." (PMID 37181807, 2023). "The present study investigated the role of STK24 in tumor angiogenesis by assessing the density of microvessel in subcutaneous tumors when induced by A549 cells expressing control, sgSTK24#1, or sgSTK24#2." (PMID 36720310, 2023). "Overall, the findings of the current study showed that STK24 positively regulates tumor angiogenesis." (PMID 36720310, 2023). "The present study also analyzed the STK24 expression levels of 69 NSCLC tumor tissues using IHC assays." (PMID 36720310, 2023). "Results of IHC assays used to determine the density of microvessels in tumors showed that silencing of STAT3 abrogated STK24-mediated tumor angiogenesis." (PMID 36720310, 2023). "In conclusion, the findings of this study demonstrated that STK24-mediated tumorigenesis, and tumor angiogenesis was dependent on STAT3/VEGFA signaling pathway." (PMID 36720310, 2023). "The results of the current study revealed that STK24-mediated tumor angiogenesis was dependent on STAT3/VEGFA signaling pathway." (PMID 36720310, 2023). "For mechanism of STK24 action, it was evident that STK24 prevents STAT3 from polyubiquitin–proteasomal–mediated degradation and STK24 regulated tumor angiogenesis through STAT3/VEGFA signaling pathway." (PMID 36720310, 2023). "PR−/ER− cases demonstrated frequent loss of LNX1 and SNORA80A, and gain of ZNF4, STK24 and CCDC191; gain of CDK20 was common in PR-high tumours." (PMID 34079052, 2021). "To investigate the role of STK24 in a native tumor environment, we examined the effects of STK24 knockdown in an orthotopic immune-competent animal model." (PMID 31892988, 2020). "The expression levels of the STK24/MST3 protein were examined by a western blot analysis in the tumor and adjacent normal gastric tissues of 39 patients." (PMID 31892988, 2020). "In this study, we found that STK24 promotes tumorigenesis by compromising tumor immunity." (PMID 38229183, 2024). "STK24 inhibition effectively overcomes tumor intrinsic resistance to anti‐PD1 therapy." (PMID 38229183, 2024). "Similarly, elevated STK24 protein expression in tumor tissues was observed when compared to matched adjacent tumor tissue controls in most of individual cases." (PMID 38229183, 2024). "In this study, we uncovered a regulatory role of STK24 in tumor immunity." (PMID 38229183, 2024). "Stk24 knockout significantly inhibited the formation of primary tumor nodules in the lung." (PMID 38229183, 2024). "Importantly, the difference in tumor growth between the Ctrl and Stk24 KO groups disappeared after anti‐CD8α mAb treatment, indicating that STK24 supports CT26 tumor development through inhibition of CD8+T cell‐dependent cytotoxic T cell responses." (PMID 38229183, 2024). "Given that the role of STK24 in tumor growth likely pertains to immune response, our investigation aimed to clarify whether such a role affects the onset and development of primary tumors." (PMID 38229183, 2024). "Given the up‐regulation of STK24 gene expression in various tumor tissues and its correlation with poor survival, STK24 could be a promising target for the development of more effective immunotherapeutic interventions." (PMID 38229183, 2024).
tumor (continued). "To verify whether STK24 in tumor cells could directly affect CD8+ T antigen‐specific killing ability, we co‐cultured OT1‐CD8+ cells with Stk24 knockdown MC38‐OVA or KPC‐OVA cells." (PMID 38229183, 2024). "As depicted, the Stk24 knockout group exhibited a drastic decrease in tumor growth." (PMID 38229183, 2024). "Furthermore, we performed in vivo assays in BALB/c nude mice and in vitro assays to show that STK24-regulated tumor angiogenesis depends on STAT3." (PMID 36720310, 2023). "Further, it was found that STK24 can positively regulate tumor angiogenesis." (PMID 36720310, 2023). "Furthermore, it was illustrated that STK24 mediated tumor proliferation and angiogenesis in a STAT3-dependent manner using in vivo and in vitro experiments." (PMID 36720310, 2023). "Moreover, it was evident that STK24-mediated regulation of tumor angiogenesis and proliferation was dependent on expression of STAT3." (PMID 36720310, 2023). "We are aware of the possibility that some STK24 protein may exist in the stromal tumor-infiltrating cells of tumor biopsies and surgical specimens and that this protein may be detected by western blot analyses." (PMID 31892988, 2020). "In the current study, the secretion of interleukin-6 (IL-6), granulocyte colony-stimulating factor (GCSF) and chemokine (C-X-C motif) ligand 16 (CXCL16) was increased by the STK24-knockdown tumor cells in comparison to the secretion by the control-pEGFP tumor cells." (PMID 31892988, 2020). "Therefore, results of the current study enhances the available understanding on tumor angiogenesis and shows that STK24/STAT3/VEGFA signaling pathway may be a novel therapeutic target for treatment of patients with NSCLC." (PMID 36720310, 2023). "Therefore, in this study, we further explored the relationship between STK24 and tumor immunity." (PMID 37181807, 2023). "To verify if STK24 mediates tumor PD‐L1 expression through an AKT activation‐dependent manner, we employed the AKT activation‐specific inhibitor MK2206 to treat Ctrl and Stk24 KO cells prior to IFN‐γ induction." (PMID 38229183, 2024). "At the molecular level, STK24 phosphorylates AKT1 at Thr21, resulting in the induction of PD‐L1 expression and facilitating tumor immune escape in vivo." (PMID 38229183, 2024). "Mouse xenograft transplantation assays was conducted to validate the obtained findings on the relationship between STK24 and STAT3/VEGFA signaling pathway in tumor angiogenesis." (PMID 36720310, 2023). "Serine/threonine-protein kinase 24 (STK24), also known as MST3, belongs to the germinal center kinase III subfamily, and the biological function of STK24 in NSCLC tumorigenesis and tumor angiogenesis is still unclear." (PMID 36720310, 2023). "By knowing that MST1/STK4 mainly functions as a tumor suppressor, while MST2/STK3 can act as an oncogene, the role of MST3/STK24 in carcinogenesis should be determined." (PMID 37181807, 2023). "STK24‐defect has no detectable effect on tumor formation in immunodeficient mice, but significantly impedes tumor growth in immunocompetent mice, accompanied by increased infiltration of cytotoxic CD8+ T cells and natural killer (NK) cells in tumor tissues." (PMID 38229183, 2024). "Collectively, these results imply that STK24 is not involved in the growth regulation of the tumors but contributes to anti‐tumor immune response." (PMID 38229183, 2024). "Clearing NK cells with the anti‐PK136 antibody yielded no statistically significant tumor growth difference between the Ctrl and Stk24 KO LLC tumors, suggesting that the anti‐tumor effect of STK24 deletion primarily depends on NK cells in the LLC tumor‐bearing model." (PMID 38229183, 2024). "When CT26 or LLC Stk24 KO mutant cells were inoculated into immunodeficient NOD‐SCID IL2rg−/− (NSG) mice, the in vivo growth of the xenografted tumor cells was indistinguishable between the Stk24 KO mutant and wild‐type controls." (PMID 38229183, 2024).